MSLN (mesothelin)
Diseases named in the same sentence as MSLN in open-access papers (continued):
Sharing a sentence is not in itself a finding about the gene and the disease.
malignant mesothelioma (continued). "The aim of this study was to assess the combination of the protein marker mesothelin in plasma and the miRNA miR-103a-3p in the cellular blood fraction in order to enhance the biomarker performance to diagnose malignant mesothelioma." (PMID 25469901, 2014). "We report the use of serum mesothelin in the assessment of patients with malignant mesothelioma in routine practice." (PMID 25227779, 2014). "The single-chain IL12-SS1 (Fv) immunocytokine bound native mesothelin proteins on malignant mesothelioma (NCI-H226) and ovarian (OVCAR-3) cells as well as recombinant mesothelin on A431/H9 cells." (PMID 24260587, 2013). "Mesothelin targets antigens for malignant mesothelioma using 111In labeled anti-mesothelin monoclonal antibody (mAbMB) coated on iron oxide nanoparticles." (PMID 23912234, 2013). "Mesothelin is a glycosylphosphatidylinositol-anchored glycoprotein that is highly expressed on the cell surface of malignant mesothelioma." (PMID 24260587, 2013). "Ability of osteopontin, soluble mesothelin and megakaryocyte potentiating factor to distinguish healthy asbestos-exposed subjects from malignant mesothelioma patients." (PMID 24281081, 2010). "In malignant mesothelioma, the mesothelin protein (MSLN) is highly expressed." (PMID 37419983, 2023). "However, patients with malignant mesothelioma expressing mesothelin diffusely (100% of positive cells on the cell membrane) had increased overall survival compared to patients whose tumors had heterogeneous or no mesothelin expression." (PMID 28460459, 2017). "The allogenic tumor lysate is an ‘off-the-shelf’ product composed of several TAAs, generated from malignant mesothelioma cell lines, containing shared antigens with PDAC, including mesothelin (MSLN), WT1, and Survivin." (PMID 40227779, 2025). "Among these angiogenesis related biomarkers, we demonstrated that Galectin-1, Mesothelin, shed SDC-1 and MMP-7 are biomarkers that discriminated best between malignant mesothelioma and metastatic adenocarcinomas." (PMID 32731396, 2020). "Higher Mesothelin, Osteopontin and VEGF levels were described earlier as individual markers in malignant mesothelioma." (PMID 32731396, 2020). "Our data shows that the level of Galectin-1 and mesothelin are significantly higher in MM patients in comparison with metastatic adenocarcinoma patients whereas, shed SDC-1 and MMP-7 levels are significantly decreased in malignant mesothelioma patients." (PMID 32731396, 2020).
lung adenocarcinoma (31 papers, 2011 to 2025). A carcinoma that arises from the lung and is characterized by the presence of malignant glandular epithelial cells. "High expression of MSLN was associated with poor prognosis of patients with breast and lung adenocarcinomas in previous studies." (PMID 35920319, 2023). "We established a human MSLN expressing syngeneic mouse model using PD-L1 positive mouse lung adenocarcinoma cell line 531LN2 stably transfected with a vector encoding hMSLN." (PMID 30400835, 2018). "In case of lung adenocarcinoma high-level of mesothelin expression is associated with aggressiveness, poor prognosis and KRAS gene mutation status." (PMID 28460459, 2017). "The overexpression of mesothelin is associated with particularly poor prognosis for patients with lung adenocarcinoma harbouring mutations in the v-Ki-ras2 Kirsten rat sarcoma viral oncogene homolog (KRAS) gene." (PMID 29113296, 2017). "Although the mechanism(s) and/or tumor biological significances were unclear, high mesothelin expression was associated with KRAS gene mutation in lung adenocarcinoma." (PMID 28460459, 2017). "This may relate to why expression of mesothelin, as assessed by immunohistochemistry, is linked to worse prognosis in a number of different cancers, but particularly in lung adenocarcinoma." (PMID 36911670, 2023). "We demonstrate here that 24% of advanced lung adenocarcinoma express high levels of mesothelin, and that high mesothelin expression is associated with EGFR wild-type and mutant KRAS and, independent of the mutation status, is associated with decreased overall survival." (PMID 26028668, 2015). "Effusion mesothelin level was only elevated in one of these samples and this was from a patient presenting with an effusion containing atypical cells associated with a primary lung adenocarcinoma." (PMID 25505814, 2014). "MSLN showed a 4.37 and 2.61 absolute fold upregulation in STK11 and KEAP1 mutated lung adenocarcinoma (LUAD) patient population, respectively." (PMID 39186767, 2024). "Remarkably, cytoplasmic MSLN immunohistochemistry signals in human lung adenocarcinoma, lung squamous cell carcinoma, and extrahepatic cholangiocarcinoma tissue samples have been previously reported and attributed to likely unprocessed protein precursors." (PMID 28898276, 2017). "In early-stage lung adenocarcinoma, a recent retrospective study found mesothelin expression in 69% of tumors." (PMID 26028668, 2015). "53% of advanced lung adenocarcinomas expressed mesothelin to some degree; high mesothelin expression, defined as mesothelin positivity in more than 25% of cells, was found in 24% of patients." (PMID 26028668, 2015). "We found that approximately 50% of advanced lung adenocarcinomas express mesothelin and high mesothelin expression, defined as mesothelin positivity in more than 25% of cells, was associated with inferior survival." (PMID 26028668, 2015). "We evaluated the intensity, and the percentage of cells expressing mesothelin in tissue obtained from 93 patients with advanced lung adenocarcinoma who underwent molecular profiling for potentially actionable genes using a multi-platform approach." (PMID 26028668, 2015). "Our results provide strong rationale to explore anti-mesothelin targeted therapies in advanced lung adenocarcinoma especially in the KRAS-mutant subgroup." (PMID 26028668, 2015). "In this study, we used prospectively obtained clinical and pathological data to characterize mesothelin expression in advanced lung adenocarcinoma." (PMID 26028668, 2015). "The results of this study and previous work by others provide strong rationale that anti-mesothelin targeted therapy should be explored as a therapeutic modality in advanced lung adenocarcinomas." (PMID 26028668, 2015).
lung adenocarcinoma (continued). "Human mesothelin has been proposed to be a malignancy factor as it increased tumor cell proliferation and migration in vitro and tumor size in nude mice and increased cell proliferation in lung adenocarcinomas: mesothelin has also been reported to increase cell invasion." (PMID 26931187, 2016). "Mesothelin expression has been demonstrated in approximately 30–70% of lung adenocarcinoma." (PMID 26028668, 2015). "Molecular diagnostics frequently employ biomarkers such as calretinin, CK5/6, WT‐1, mesothelin (MSLN), and D2‐40, whereas lung adenocarcinoma biomarkers typically include TTF‐1, napsin A, CEA, BerEP4, and claudin‐4." (PMID 40904706, 2025). "Later screening with an antibody clone that worked on fixed tissue sections (5B2) revealed mesothelin is absent from small cell lung cancer, but is expressed by approximately half of lung adenocarcinomas." (PMID 36911670, 2023).
ovarian tumors (31 papers, 2006 to 2024). "In the context of developing more effective anti-MSLN antibodies, understanding the glycan structures associated with MSLN is necessary, as the binding of CA-125 to MSLN, which facilitates metastasis of ovarian tumors, appears to be dependent on glycosylation states of MSLN." (PMID 36968141, 2023). "In addition, this study evaluated if the in vivo CD25 Ab depletion could generate anti-tumor effects via enhancing antigen-specific immunity using mesothelin, a novel ovarian tumor-associated antigen." (PMID 23082146, 2012). "MSLN has been shown to bind to CA-125 and is thought to play a role in the peritoneal diffusion of ovarian tumor cells." (PMID 38918474, 2024). "The interaction of MUC16 with mesothelin has been shown to mediate cell adhesion and facilitate peritoneal metastasis of ovarian tumors." (PMID 38197671, 2024). "G11 CAR-T cells significantly inhibited the growth of MSLN-positive ovarian tumor cells, increased the secretion of cytokines, effectively inhibited tumor growth and had relatively high antitumor activity in vivo." (PMID 39023820, 2024). "In that study, a recombinant protein containing a mini-antibody to mesothelin, which is highly expressed in a mouse model of ovarian tumor, and mycobacterial HSP70 was produced and tested." (PMID 38391930, 2024). "Mesothelin (MSLN) is a candidate immunotherapy target; it is overexpressed by ovarian tumors and contributes to malignant/invasive phenotypes, making tumor antigen loss disadvantageous." (PMID 35264436, 2022). "We further found that the overexpression of MSLN was closely related to the poor prognosis of patients with ovarian tumors." (PMID 35692779, 2022). "Our results show that deletion of host MSLN expression alters the ultrastructure of tumor susceptible host tissues, decreases MCA size and significantly decreases intraperitoneal ovarian tumor burden." (PMID 34830322, 2021). "Overall, deletion of host MSLN expression resulted in a less favorable microenvironment for ovarian tumor cell adhesion and metastatic anchoring." (PMID 34830322, 2021). "Deletion of host MSLN expression decreased ovarian tumor cell adhesion to peri-ovarian and uterine adipose suggesting a role of host MSLN expression in initial tumor cell adhesion." (PMID 34830322, 2021). "Evaluation of other internalizing receptors expressed on a higher proportion of ovarian tumors than HER2 such as mesothelin is also of interest." (PMID 26840082, 2016). "This is also the first report of an antigen specific immune response in hens with tumors, and similar to humans serum mesothelin autoantibodies only occur in response to ovarian tumors that express mesothelin." (PMID 21801396, 2011). "In our study using a chicken specific primer for RT-PCR analysis showed that mesothelin mRNA was increased significantly in hen ovarian tumors compared to normal ovaries." (PMID 21801396, 2011). "Anti-mesothelin antibodies were assessed by immunoassay of sera from hens with normal ovaries and with ovarian tumors." (PMID 21801396, 2011). "The presence of a humoral immune reaction to ovarian tumors in the hen suggests it will be possible to use the hen for pre-clinical studies of anti-mesothelin vaccines." (PMID 21801396, 2011). "In this study we utilize recombinant-Fc tagged human mesothelin to measure the binding kinetics of this glycoprotein to MUC16 expressed on the ovarian tumor cell line OVCAR-3." (PMID 17067392, 2006). "The mucin MUC16 and the glycosylphosphatidylinositol anchored glycoprotein mesothelin likely facilitate the peritoneal metastasis of ovarian tumors." (PMID 17067392, 2006). "We also demonstrate that MUC16 positive ovarian tumor cells exhibit increased adherence to A431 cells transfected with mesothelin (A431-Meso+)." (PMID 17067392, 2006). "A recombinant fragment of MUC16 composed of the cytoplasmic region and a partial tandem repeat domain binds to mesothelin, a glycoprotein that is highly expressed by ovarian tumors and mesotheliomas." (PMID 17067392, 2006).
ovarian tumors (continued). "We show that MCA compactness is associated with the co-culture of mesothelial cells with ovarian tumor cells suggesting the importance of mesothelial cells in compact MCA formation regardless of MSLN expression." (PMID 34830322, 2021). "Overall abdominal tumor burden was significantly decreased in MSLNKO mice, most notably impacting metastatic colonization of omental, ovary and liver tissues, suggesting host MSLN expression is important in the metastatic success of ovarian tumor cells and in the progression of the disease." (PMID 34830322, 2021). "Thus, specific molecules expressed by ovarian tumors, such as mesothelin, can be used as targets for the delivery of antigeneic CTL peptides." (PMID 24354786, 2013). "Mesothelin mRNA expression was analyzed by RT-PCR in hen ovarian tumors and normal ovaries." (PMID 21801396, 2011). "In addition to elevated expression of mesothelin in ovarian tumors, there was evidence of circulating mesothelin antibodies in hens with ovarian tumors." (PMID 21801396, 2011). "These experiments suggest that mesothelin may play an important role in the metastasis of the ovarian tumors within the peritoneum." (PMID 17067392, 2006). "Moreover, examination of tumor-infiltrating CAR-Ts demonstrated that both CAR-T products exhibited elevated levels of immunoinhibitory receptor (LAG3 and PD-1) expression which coincided with the expression of relative ligands (HLA-DR and PD-L1) by mesothelin-positive ovarian tumors." (PMID 38146364, 2023). "However, MSLN is overexpressed in human ovarian tumors and correlates to poor survival." (PMID 34830322, 2021). "Current studies that have reported that HE4 and mesothelin could be used as ovarian tumor markers." (PMID 32771026, 2020). "Consequently, MSLN:CA125-dependent cell attachment may play an important role in the peritoneal implantation of ovarian tumor cells." (PMID 30134520, 2018). "Indeed, we have previously utilized mesothelin for targeting ovarian tumor cells." (PMID 24354786, 2013). "More abundant transcripts in LGSC-PT included the CA-125 binding partner mesothelin (MSLN) and the serine protease KLK6, which predicts the recurrence of borderline and low-grade ovarian tumors and is regulated by MAPK29." (PMID 38014221, 2023). "The MSLN-Hsp70 protein combines a scFv to mesothelin (MSLN), an antigen overexpressed in pancreatic and ovarian tumors, and a heat shock protein from Mycobacterium tuberculosis (Hsp70)." (PMID 25806106, 2015). "It remains to be demonstrated if simultaneous utilization of antibodies directed against mesothelin, CD44 and β-1 integrins will substantially inhibit binding of ovarian tumor cells to the mesothelium." (PMID 17067392, 2006). "Here, we have constructed CAR T cells based on mesothelin polypeptide sequences that bind MUC16 to effectively eliminate MUC16-expressing ovarian cancer tumor cells and stem cells in vitro, as well as to eliminative ovarian tumor xenografts in vivo." (PMID 38637885, 2024). "Likewise, there is a growing list of proteins expressed in chicken ovarian tumors such as CA125, mesothelin, COX 1, Selenium Binding Protein 1, E-cadherin and VEGF that are similarly altered in human ovarian tumors." (PMID 24040191, 2013). "Significant mesothelin mRNA expression was observed in 57% (12/21) of hen ovarian tumors but not in normal ovaries and was found predominantly in serous tumors as in humans." (PMID 21801396, 2011). "The results demonstrate for the first time that, similar to human ovarian tumors, mesothelin mRNA and protein are expressed in hen ovarian tumors and not in normal ovaries." (PMID 21801396, 2011). "This hypothesis is also supported by the observation that both mesothelin and MUC16 are co-localized in immunohistochemical studies of ovarian tumors." (PMID 17067392, 2006). "Mesothelin, like MUC16, is overexpressed by the ovarian tumor cells." (PMID 17067392, 2006).
ovarian tumors (continued). "The lower affinity of mesothelin for soluble MUC16 also makes it less likely that the mucin can act as a cross-linking agent by attaching to mesothelin expressed on the mesothelial and the ovarian tumor cells." (PMID 17067392, 2006). "FOLR1 and MSLN were highly and specifically stained on the surface of ovarian tumor cells, while almost no significant staining was observed for FOLR1 or MSLN in normal ovarian tissue specimens." (PMID 34803504, 2021).
cervical carcinoma (21 papers, 2014 to 2026). A carcinoma arising from either the exocervical squamous epithelium or the endocervical glandular epithelium. "engineered NK cells with a third-generation CAR targeting MSLN, a tumor-associated antigen overexpressed in primary human cervical carcinomas and established cell lines, as evidenced by their study and prior research." (PMID 41181137, 2025). "High mesothelin expression was associated with poor OS in patients with common histological cervical cancer types." (PMID 40697656, 2025). "MSLN has been identified as upregulated in cervical cancer tissue samples and proposed as a tumor-associated antigen or a target for cervical cancer therapy." (PMID 36992411, 2023). "High MSLN expression was associated with poor OS in patients with common histological cervical cancer types." (PMID 36434635, 2022). "This review summarizes the state of the art on the biological role, diagnostic value, prognostic significance, and therapeutic potential of MSLN in ovarian, endometrial, and cervical cancers." (PMID 42279275, 2026). "HER2, with an overexpression rate of 38%–94% in cervical cancer, and mesothelin, with an overexpression rate of approximately 25%, are the primary antigens currently targeted by CAR‐T cells in cervical cancer." (PMID 40525700, 2025). "Consistently, we observed similar cytotoxicity of T cells expressing a mesothelin-targeted CAR composed of varied CD3 ICDs when cocultured with human cervical cancer HeLa cells that endogenously express mesothelin." (PMID 39809749, 2025). "Given the limited expression of mesothelin in normal tissues, targeting it for the treatment of cervical cancer is a viable strategy." (PMID 40697656, 2025). "Anti-Mesothelin CAR-NK anti-cervical cancer activity was assessed in 2D and 3D co-culture experiments that showed more effective elimination of cancer cells by CAR-NK cells as compared to control NK cells." (PMID 39781381, 2024). "Our data further indicate the suitability of CAR-based therapy approaches for solid cancers, as the anti-Mesothelin CAR-NK-92 cells showed strong anti-cervical cancer cytotoxicity in several 2D and 3D model systems." (PMID 39781381, 2024). "Anti-Mesothelin CAR-NK cells demonstrated high cytotoxicity against cervical cancer cells in 2D and 3D culture models, which corresponded to increased degranulation of CAR-NK-92 cells upon exposure to Mesothelin+ target cells." (PMID 39781381, 2024). "Mesothelin- cervical cancer cells were generated by CRISPR-Cas9-mediated knockout and used to show target antigen specificity of anti-Mesothelin CAR-NK-92 cells and primary NK cells derived from different healthy donors in co-culture experiments." (PMID 39781381, 2024). "Flow cytometry was used to evaluate Mesothelin surface expression on several cervical cancer cell lines that represent different disease entities, including cervical squamous cell carcinoma (SiHa, CaSki) and adenocarcinoma (HeLa)." (PMID 39781381, 2024). "To investigate the cytotoxicity of anti-Mesothelin CAR-NK cells against cisplatin pre-treated cervical cancer cells, we performed co-cultures and monitored the remaining target cells by live-cell imaging." (PMID 39781381, 2024). "Our study shows that CAR-NK-92 cells directed against Mesothelin are effective against cervical cancer cell models in in vitro assays." (PMID 39781381, 2024). "Apart from cervical cancer, Mesothelin has also been considered as a target for different malignancies." (PMID 39781381, 2024). "A study that investigated 79 primary cervical cancer tissues identified high Mesothelin expression in the majority of cervical cancers, with higher expression levels being detected in adenocarcimonas (77%) than in squamous cell carcinomas (57%)." (PMID 39781381, 2024). "Taken together, the low expression profiles of Mesothelin in healthy adult tissue and high expression in most cervical cancers, make it a promising target antigen for immunotherapeutic approaches." (PMID 39781381, 2024).